CD4 (CD4 molecule)
Diseases named in the same sentence as CD4 in open-access papers (continued):
Sharing a sentence is not in itself a finding about the gene and the disease.
infection (continued). "This regimen successfully depleted the CD4+ T cells in the first week and prevented the recovery of body weight in GITRL tg mice in the second week of the infection with LCMV." (PMID 25738498, 2015). "In the Status Quo scenario, HIV-infected MSM spent an average of 7.4 years after infection before initiating ART, which occurred when the median CD4+ T-cell count was 148 cells/mm3(25th-75th percentiles: 52–266)." (PMID 26302044, 2015). "Similar to Tfh responses during primary infection, Tfh responses during second P. chabaudi infection and IFN-γ responses of CD4+ T cells during primary and second P. chabaudi infection were not altered by the absence of IL-21 signaling." (PMID 25763578, 2015). "When the mice were analyzed at 20 days post-infection (the first detectable copies of HIV-1 RNA were seen on day 13), the ratio of CD4+/CD8+ T cells was above 1 in all tissues." (PMID 26034905, 2015). "At 6 days after infection, similar levels of CD28 were observed on CD4+ T cells and TFH cells from old and adult mice, suggesting that decreased expression of co-stimulatory molecules was not responsible for the delayed germinal center development in old mice." (PMID 26204259, 2015). "Viral clearance requires both CD4+ and CD8+ T cells, and depletion of either subset permits persistent but subclinical infection." (PMID 26495972, 2015). "Next, we compared the expression levels of activation markers on the cell surface of CD4+ and CD8+ T cells derived from GIFT7-treated group and others at day 7 post infection." (PMID 26131365, 2015). "A cross-sectional study in CI on ART subjects revealed that nTregs, DP and mTh17 counts were negatively correlated with the time post-infection ART was initiated and positively correlated with nadir CD4 counts." (PMID 25924895, 2015). "Interestingly, several of the polymorphisms identified in this study reverted following infection into hosts no longer able to target the epitope, suggesting CD4+ T cell-induced escapes impose a viral fitness cost as has been demonstrated extensively for CD8+ T cells." (PMID 26302050, 2015). "When the mice were analyzed at 42 days post-infection, the ratio of CD4+/CD8+ T cells was below 1 and this ratio continued to decrease as the infection progressed." (PMID 26034905, 2015). "Consistent with the minimal contribution from residual T cells following lethal irradiation, we verified that the CD45.2:CD45.1 ratio in peripheral blood was 1:1, with similar proportions of CD4, CD8 T cells and Foxp3+ Tregs prior to infection." (PMID 25590581, 2015). "For the trans-infection assays, we limited MDDC exposure to virus to 1 hour, before washing and co-culturing with autologous PHA, IL-2 stimulated CD4+ T-cells." (PMID 25809903, 2015). "By week 10 of infection, anti-CD25-treated mice showed diminished numbers of CD4+ and CD8+ T lymphocytes in the lungs, indicating that the reduction in the number of Tregs did not cause exacerbated inflammatory reactions." (PMID 26512987, 2015). "Addition of cART at the time of infection inhibited the expression of HIV proteins at day 6 post-infection, indicating that the FACS detected de novo viral protein expression rather than the presence of virions from the inoculum on the surface of CD4 T cells." (PMID 26539983, 2015). "The role of immunity against B. microti was studied in mice which showed necessity for CD4+ T cells and IFN-γ in conferring immunity against infection." (PMID 26693364, 2015). "Further research is needed to examine the role of CD4+ and/or CD8+ T memory cells in protection against aMPV infections." (PMID 25889279, 2015). "In order to study the dynamics of CD4, CD8 and CD20 cells, the samples were recovered in peripheral blood, LNs (axillary and inguinal LNs) and spleen, over the time course of infection." (PMID 26640894, 2015).
infection (continued). "The flow cytometric analysis of the spleens from IP infected animals, 11 days after infection, showed a decrease in the number of CD8+ T lymphocytes and a slight increase of CD4+." (PMID 26469517, 2015). "To this aim, we used a recombinant virus, mutated in the env gene and pseudotyped with Vesicular Stomatitis Virus G-protein (VSV-G), which enters macrophages through a CD4/CCR5-independent pathway and completes only a single round of infection." (PMID 25608886, 2015). "We first showed that CD4+ and CD8+ T lymphocytes display higher expression of CD69 after infection with Y strain and Col cl1.7, showing that both strains induce T cell activation." (PMID 26147698, 2015). "recombinant proteins; although the CD4+ T cells response had been more important in the IFN-γ production, as well as in the induction of protection against challenge infection." (PMID 26367128, 2015). "During the acute phases of the infection, either before or after OVA-sensitization, an increased number of CD4+CD25+Foxp3+ cells with suppressive activity were observed in the spleen of Trichinella-infected mice." (PMID 26114122, 2015). "La manifestation clinique de l'infection à HHV8 dans notre cohorte qu'est le sarcome de Kaposi paraît associée au stade avancé du VIH/SIDA, et un taux bas de CD4+." (PMID 26090027, 2015). "In contrast to acute phase patients, similar total CD4+ and CD8+ T-cell responses were observed at 3 and 32 weeks post-infection." (PMID 26606759, 2015). "Relevant to our naïve CD4+ T cells findings, the DLNs from old mice had nearly a 10-fold decrease in the naïve T cell chemoattractant CCL21 at day 2 after infection." (PMID 26204259, 2015). "In the IG infected mice there was a reduction (41%) of CD4+ and maintenance of CD8+ values after 26 days of infection." (PMID 26469517, 2015). "We found similar numbers of GP66-specific CD4+ T cells in WT and GITRL tg mice at different time points during the first three weeks of infection, indicating that the overall induction of anti-viral CD4+ T cell responses was unaltered." (PMID 25738498, 2015). "In these patients classified as stage 4 infection, it is strongly recommended that HAART should be commenced with CD4 cell count of ≤500 cells/mm325." (PMID 26136407, 2015). "As a positive control for GrB expression, infection with a sublethal dose of PR8 was used and induced >97% GrB+ CD4 and CD8 cells as expected." (PMID 26161083, 2015). "Treating resting CD4+ T cells with CCL19 increased productive infection 2-fold over untreated cells, while IL-7 treatment produced a 5-fold increase in productive infection." (PMID 26067822, 2015). "When we consider the significance of the cell-to-cell infection in patients infected with HIV-1, it should be noted that the environment of immune cells including CD4+ T-cells in vivo is radically different from the conditions of in vitro cell cultures." (PMID 26441404, 2015). "Once infection has occurred, HIV rapidly depletes CD4+ T cells from the GALT as a larger percentage of these cells express elevated level of CCR5, the coreceptor for cellular entry, compared to peripheral blood." (PMID 25759844, 2015). "The highest number of IL-21-producing CD4+ T cells co-expressing IFN-γ and IL-10 was detected at day 15 post-infection." (PMID 25763578, 2015). "It falls from around 1 before infection towards 0 as HIV-1 progresses (because NM is a constant and N, the total density of CD4+ T cells, gradually declines with the HIV-1 progression)." (PMID 25837979, 2015). "The percentage of CD4+CD25+ cells in lymph organs, e.g., the thymus, spleen, bursa of Fabricius and peripheral blood, during the first 1–5 days post infection (dpi) was assessed by flow cytometry." (PMID 25803101, 2015). "In contrast, by day 7 and 10 post infection significantly higher percentage and absolute number of IFN-γ-producing CD4+ T cells were detected in IL-27R-/- mice as compared to wild-type cohorts." (PMID 26222157, 2015).
infection (continued). "It is generally accepted that IFNγ plays a key role in early stages of infection and CD8 and CD4 T cells have been indirectly suggested to be the sources of IFNγ during T. b. brucei infection." (PMID 26070118, 2015). "CD4-depleted GITR+/+ mice had fewer and less functional LCMV-specific CD8 T cells, and 100-fold higher viral load relative to non-CD4-depleted GITR+/+ mice, consistent with previous reports of CD4 depletion increasing the severity of LCMV cl 13 infection." (PMID 25590581, 2015). "The sequestration of CD4+ and CD8+ T cells to the brain was examined on day 7 post-infection to determine if the decreased expression of trafficking-associated genes correlated with a reduction in the chemotaxis of T cells to the brain." (PMID 25768944, 2015). "In contrast, the proportions of B220+, CD4+ and CD8+ lymphocytes, as well as MZ MOMA+ macrophages decrease significantly as infection progresses." (PMID 26068006, 2015). "CD4+ T cell counts of RPs decreased rapidly at a rate of 46 cells/μL/year, before patients (RPs) received ART after infection for 2 years." (PMID 26286082, 2015). "At day 14 after infection, the percentage of IFN-γ+ CD4+ T cells is higher in the lungs of mice treated with α-DEC-ESAT than in non α-DEC-ESAT-treated mice." (PMID 25915045, 2015). "FI-RSV alone immune mice showed low levels of pDCs and CD4+ DCs, which is similar to those in PBS control infection or live RSV re-infected mice." (PMID 26468884, 2015). "Il faudrait signaler que cette prévalence était tout de même moins élevée dans la tranche d'âge de 31 à 40 ans, en stade précoce de l'infection à VIH (stades 1 et 2), et chez les personnes ayant un taux bas de CD4+ (<200)." (PMID 26090027, 2015). "In human recurrent herpes lesions, CD4 T cells infiltrate first, followed by CD8 T cells which correlates with termination of the infection." (PMID 25875649, 2015). "Total RNA was isolated from CD4+ and CD8+ T cells sorted by FACS based on the expression of the CD43 marker and purified from the livers of wild-type mice at 30 days post-infection." (PMID 25874567, 2015). "Eight days after infection, proportions of NP309–328-specific CD4+ T cells were also reduced in both the spleen and liver of TTR-NP mice compared with B6 mice." (PMID 28210682, 2015). "Interestingly, early after infection, at d7, there was an increase (p<0.05) in the total number of I-AbHA211 and I-AbNP311-specific CD4+ T cells in the MedLN of oseltamivir-treated mice as compared to controls, where at d10, virus-specific CD4+ T cell numbers were equivalent in the MedLN." (PMID 26086392, 2015). "As an immediate interaction response, at early time points several immune cells including monocyte/macrophage, CD4+CD25−CD127− Tr1 and CD4+CD25+CD127low/− iTreg cells produce IL-10 in both SbS and SbR-LD infection." (PMID 25032977, 2014). "In contrast, B cell and T cell [both CD4 and CD8] influx into the lung progressively increased over the study period of 7 days post-infection." (PMID 24847941, 2014). "The depletion (<518 CD4+/mmc) persisted in the post-acute and chronic phases of infection with the exception of monkeys AI075, which experienced a stable, although partial, CD4+ T cell recovery (699−1,239 CD4+/mmc)." (PMID 25356594, 2014). "For secondary LVS IP challenges, either CD4+ or CD8+T cell subsets are sufficient for survival and clearance of an LVS infection." (PMID 24400128, 2014). "In general, it is thought that LCs express HIV-1 receptor CD4 and CCR5 coreceptor, which allows productive infection with only R5 HIV-1 and selective transmission of R5 strains through a cis pathway." (PMID 24990163, 2014). "Studies on individuals with acute HCV infection have demonstrated that an early, strong and multispecific CD4 and CD8 T-cell responses are related to the resolution of infection." (PMID 25705565, 2014). "Following infection with HIV-1, human CD4 T cells were depleted from the lamina propria, as previously reported." (PMID 24497830, 2014).
infection (continued). "Regarding the effect of T. cruzi on lymphocyte apoptosis, it is already well known that murine splenic CD4+ and CD8+ T lymphocytes increase the expression of CD95 after infection in mice; this effect is correlated with activation-induced cell death." (PMID 25371910, 2014). "Mice previously infected as neonates had a peak influx of both CD4 and CD8 T cells at day 7 after infection." (PMID 24173217, 2014). "Altogether, these data indicate that depletion of CD4+ T-cells prior to SIV infection results in activation of monocyte and massive infection of tissue-resident macrophages." (PMID 25356757, 2014). "It is important to note that in our experiments primary CD4+ T cells were activated and expanded in standard RPMI containing glucose for up to five days prior to infection with HIV-1 and subsequent provision of either glucose or galactose." (PMID 25421745, 2014). "The percentages of CD3+ CD4+ and CD3+ CD8+ cells increased in the cerebrum in the first 7 days of infection." (PMID 24473125, 2014). "Total splenocytes were then harvested on day 7 after infection (day 3 post-transfer), and IL-10 production by donor OTII and recipient T cells (distinguished based on CD90, CD4, CD8 and CD45.1/2 expression) was measured." (PMID 24613988, 2014). "The aggregate infectivity data confirms that subtype C Envs do, indeed, achieve a higher level of infection in response to increasing CCR5 levels, especially when CD4 levels are limiting (compare the lower left quadrants)." (PMID 24957778, 2014). "The MAGIC-5 cell line is a HeLa cell derivative modified to express CD4 (the primary receptor) and CCR5 (the coreceptor), respectively, for the infection by SIVmac239 and CCR5-tropic HIV-1." (PMID 25519983, 2014). "Nevertheless, there is a significant population of CD4 T-cells expressing CXCR4 in the mucosa of the female genital tract, so its importance in the acquisition and development of infection needs to be clarified." (PMID 25313360, 2014). "Parasite-specific splenic CD4 T cells up-regulate PD-1 and LAG-3 and become exhausted by day 30 after mice infection with P. yoelii–infected RBCs." (PMID 24551250, 2014). "In fact, we did observe significant decrease in the percentage of IL17-secreting CD3+CD4+CD25− T cells and a significant increase in splenocyte secretion of IL-10, a cytokine secreted by Treg cells, following infection with BCG-TB1860, compared to BCG-GFP." (PMID 24945624, 2014). "CD4+ T cells were infected with HIV-1NL4.3-eGFP-BaL, cocultured with MDM for 3 days to approximate a single-cycle MDM infection, washed, and imaged." (PMID 25467409, 2014). "Infection of TLR4−/− mice with JEV exhibited the expansion of pDC and NK cells, and enhanced JEV-specific CD4+ and CD8+ T cell responses, which are involved in viral clearance at early and late phases of infection, respectively." (PMID 25188232, 2014). "At day 6 and 18 post-infection, portions of the cultured cells were stained with anti-CCR5 and anti-CD4 antibodies followed by FACS analysis, and genomic DNA were extracted from another portion of cells and subjected to T7 endonuclease I assay." (PMID 25541967, 2014). "In control pigs, IFN-γ secreting cells increased simultaneously with CD4–CD8α+ effector cells, as reported under experimental conditions (SPF piglets, asymptomatic infection)." (PMID 24735253, 2014). "In vivo neutralization of IFN-I by antibody administration promoted resolution of chronic LCMV Cl13 infection, allowing the restoration of functional anti-viral CD8 T cell responses at least in part through CD4 T cell- and IFN-γ-dependent mechanisms." (PMID 25400632, 2014). "Further, gp120 interacts with CD4, which is expressed by immature megakaryocytes, which also express CCR5, and leads to their infection." (PMID 25566260, 2014). "Further, pretreatment of immature DC with chloroquine prior to infection with BCG-dHCM, inhibited the production of IFN-γ from naïve CD4+ T cells." (PMID 24690183, 2014).
infection (continued). "Percentages of circulating CD4 and CD8 T cells decreased from day 9 pi onwards during the 1st infection (p<0.05, except for CD8 T cells on day 14 pi)." (PMID 24465641, 2014). "The time from infection to diagnosis is an important parameter in averting new HIV infections, which was indicated by comparison at different CD4 cell count levels." (PMID 25580461, 2014). "Surprisingly, modest but significantly higher levels of total T cells (TCRβ+) including higher levels of CD4 (CD44+) and CD8 (CD44+) T cells were detected in the lungs on day 3 post-infection." (PMID 24809749, 2014). "VL and CD4+ and CD8+ T cells were analyzed at 4, 8, 12 and 16 weeks after infection from the 100 μl of blood collected immediately following MRS and DTI studies." (PMID 25523827, 2014). "That is, we asked if escape occurs early during infection in the plasma, is the turnover of SIV DNA in resting CD4 T cells fast, and if escape occurs later in infection, is the turnover of SIV DNA in resting CD4 T cells slow." (PMID 24710023, 2014). "Although HIV can infect macrophages, CD4+ T cells are the main target cell supporting HIV replication and allowing the establishment of productive infection to drive the pathogenesis of the disease." (PMID 24404168, 2014). "These factors included a Western European origin (odds ratio [OR], 1.35, P = 0.008), CD4 cell count (square root transformed) (OR: 0.82, P = 0.01), MSM (OR:1.80, P < 0.0001), subtype B (OR:2.06, P < 0.0001) and recent infection (OR:1.43, P = 0.001)." (PMID 25047543, 2014). "In saponin + LAg vaccinated mice, we were surprised that IFN-γ secreted from both CD4+ and CD8+ T cells actually increased post-infection (p < 0.001 compared to controls), despite the failure of this vaccine regimen to induce protection." (PMID 24428931, 2014). "Together, these assays demonstrate, as expected, that when CD4 is knocked down in shCD4-macrophages HIV-1 fusion, reverse transcription, as well as productive infection are all reduced." (PMID 24465876, 2014). "To further probe the inhibitory mechanism of PGE2, we used a virus-cell infection system that utilizes an indicator cell line, TZM-bl, which has been engineered to express CD4 and CCR5." (PMID 24586238, 2014). "When monocytes were depleted by CL administration late in the course of infection, there were significant decreases in sequestered CD8+ T, as well as CD4+ T and NK cells within the brain compared to sham depleted controls." (PMID 25033406, 2014). "Here we have examined the CD4 T cell response to de novo infection with influenza virus in young and aged C57BL/6 mice, using a tetramer specific for an immunodominant CD4 T cell epitope, NP311–324/IAb." (PMID 24999367, 2014). "As expected, there was strong CD4+ T cell response (proliferation and IFN-γ production) at all times (3, 6 and 12 weeks) post-infection." (PMID 25233487, 2014). "As early as 1 hour after viral challenge, REAF protein levels are depleted in HeLa-CD4 cells, yet REAF mRNA levels remain constant throughout infection." (PMID 24410916, 2014). "This differential activation of CD4+ and CD8+ T cells by high and low dose infections respectively, was imprinted during in vitro and in vivo recall responses in healed mice." (PMID 25412267, 2014). "Conversely, the involvement of both CD4+ and CD8+ cells in terms of lymphoproliferative response upon PCV2 infection appeared to be important to evaluate, as previously demonstrated under experimental conditions." (PMID 24735253, 2014). "While low dose infection preferentially activates CD8+ T cells, high dose infection leads to preferential activation of CD4+ T cells." (PMID 25412267, 2014). "While all were able to survive the infection, at day 14, endogenous CD4+ and CD8+ T cell compartments in cancer mice continued to contain higher frequencies of CD4+PD-1+BTLA+ and CD8+BTLA+ T cells." (PMID 24796533, 2014).